CD44 (CD44 molecule (IN blood group))
Diseases named in the same sentence as CD44 in open-access papers (continued):
Sharing a sentence is not in itself a finding about the gene and the disease.
medulloblastoma (5 papers, 2014 to 2023). A malignant, invasive embryonal neoplasm arising from the cerebellum. "In the medulloblastoma cryosection, CD44 was less prominent, but both sphere and adherent cell cultures were enriched for CD44." (PMID 26183281, 2015). "CD44 overexpression eliminated the pro-apoptotic effects of miR-34a which is similar to what’s observed in medulloblastoma." (PMID 25551284, 2014). "When hAT-MSCs were co-cultured with medulloblastoma-BTICs, the expression levels of CCR4, CCR5, CCR7, XCR1, CXCR1, CXCR4, PDGFR-bb, KDR and TEK were increased, while the levels of CX3CR1, IL1R, IL6R, IL8R, IGF1R and CD44 were decreased (p<0.05)." (PMID 26076490, 2015).
mesenchymal tumors (5 papers, 2012 to 2023). "Previous DNA and RNA-driven molecular subtyping predicts EGFR expression in the classical subset of glioblastoma tumors and CD44 expression in mesenchymal tumors." (PMID 32573435, 2020). "A differential diagnostic method with IHC staining using a combination of several monoclonal antibodies against LMP2/β1i and other candidate cellular factors, such as caveolin 1, cyclin B, cyclin E, Ki-67/MIB1, and CD44, has been investigated for uterine mesenchymal tumors, including uLMS." (PMID 34563053, 2021). "Therefore, we examined the expression status of five factors and CD44 in the tissues of intravenous leiomyomatosis and compared them with the expression status of each factor in various mesenchymal tumors." (PMID 34563053, 2021). "High expressions of CHI3L1, CD44, SERPINE1, and CTGF, typical of mesenchymal tumors, were also observed." (PMID 32171051, 2020). "The HC-AFW1 cell line also expressed epithelial cell markers such as E-Cadherin, CD326 and cytokeratins as well as Vimentin, CD44 and CD133, proteins that are often found in epithelial and mesenchymal tumours." (PMID 22666492, 2012).
metastatic colorectal cancer (5 papers, 2012 to 2023). "Here, we aimed to investigate the correlation between CD44 expression and the clinicopathological features and survival of metastatic colorectal cancer (mCRC) patients." (PMID 36831554, 2023). "Here, we aimed to investigate the correlation between CD44 expression and the clinicopathological features and survival in metastatic colorectal cancer (mCRC) patients." (PMID 36831554, 2023). "In our study, we analyzed the role of CD44 expression as a prognostic marker in patients with metastatic colorectal cancer." (PMID 36831554, 2023). "In a recent study, the CD133+ CD44+ CD54+ subpopulation of CTCs has a prognostic value in metastatic colorectal cancer and shows a significant survival improvement in patients who did not undergo surgical treatment for metastasis." (PMID 30282914, 2018). "Recently, it was shown that in CTC of NSCLC patients the CD44(+)/CD24(−) population possess epithelial–mesenchymal transition characteristics, while another study in metastatic colorectal cancer has shown the prognostic significance of CTC that express both EMT and stem-like genes." (PMID 31261917, 2019).
Myocardial fibrosis (5 papers, 2018 to 2024). "TSG-6 attenuates oxidative stress through activation of CD44, and downregulates TGF-β by suppressing plasmin activity, which could result in decreased myocardial fibrosis." (PMID 30517097, 2018).
neuroendocrine tumors (5 papers, 2019 to 2025). "Neural crest-derived neoplasms tend to be CD44-negative while CD44 expression is more consistent for endoderm-derived neuroendocrine tumours." (PMID 35805976, 2022). "Next, we identified and characterized the bronchial carcinoid TIC population by the expression of stemness markers, ALDH1, CD44, Oct-4, Sox-2 and Nanog, appropriate markers based on previous studies on neuroendocrine tumors." (PMID 31470802, 2019). "This discrepancy could possibly be explained by the fact that PT tissue has an embryological origin in the neural crest, which is CD44(−), whereas neuroendocrine tumors that are CD44(+) originate from the endoderm." (PMID 40149663, 2025). "The lack of CD44 in parathyroid tissues and tumours might seem unusual considering that chromogranin A expression in parathyroid neoplasms indicates neuroendocrine differentiation, and several other neuroendocrine tumours express CD44, although it is not a specific neuroendocrine marker." (PMID 35805976, 2022).
Oral leukoplakia (5 papers, 2021 to 2025). A thickened white patch on the oral mucosa that cannot be rubbed off. "Comparison of paired associations of total protein, SolCD44, mean number of CD44 expressed epithelial layers in leukoplakia tissue, and macrophages below the basement membrane between control group and patients with leukoplakia showed statistically significant results (p < 0.0001)." (PMID 34830890, 2021). "The authors identified a significant relationship between SolCD44 levels and CD44 expression in tissue, as well as direct associations between high SolCD44 levels and intense membrane and intra-cytoplasmatic CD44 expression, as we also proved in our study with 50 oral leukoplakias." (PMID 34830890, 2021). "We observed CD44-labeled macrophages in lamina propria in the control group, but five times more of these labeled cells were found under leukoplakia." (PMID 34830890, 2021). "Comparison of the mean number of CD44 expressed in epithelial layers in leukoplakia tissue and clinical forms of oral leukoplakia showed low correlation." (PMID 34830890, 2021). "Diagnostic accuracy of CD44 and TGF-B for differentiation of SCC from dysplastic leukoplakia was assessed." (PMID 33681421, 2021). "In homogenous oral leukoplakia, the membranous expression of CD44 glycoprotein was in, on average, 19 layers of the epithelium." (PMID 34830890, 2021). "Our data also showed a tendency of the number of positive SolCD44 test lines to be increased in cases when the CD44 antigen expression in leukoplakia tissue was not only in the oral epithelial cell membrane, but also in its cytoplasm." (PMID 34830890, 2021). "Statistically significant differences between higher total protein level and clinical forms of oral leukoplakia (p < 0.0001), as well as CD44-labeled epithelial cell layer decrease (p < 0.0001), were found." (PMID 34830890, 2021). "Levels of statistical significance, when comparing the mean number of positive CD44 protein expression in epithelial layers in leukoplakia tissue and clinical forms of oral leukoplakia, were weakly expressed (** p < 0.01, *** p < 0.001)." (PMID 34830890, 2021). "CD44 antigen expression was determined in the surgical material and biopsies of oral leukoplakia and healthy mucosa." (PMID 34830890, 2021). "A statistically significant negative correlation was obtained also between higher total protein level and decrease in epithelial layers with positive immunohistochemical expression of CD44 in leukoplakia tissue (p < 0.0001)." (PMID 34830890, 2021). "In this study, we wished to explore whether and how pan-CD44 protein expression in leukoplakia tissues correlates with the positive saliva biomarker SolCD44 test and total protein with its color change on a gradient scale." (PMID 34830890, 2021). "The aim of this study was to determine whether and how pan-CD44 protein expression in leukoplakia tissues correlates with positive SolCD44 test presence and their role in oral leukoplakia." (PMID 34830890, 2021). "Analyzing the male group, a statistically significant negative correlation was observed in the terms of total protein level being higher (indicated by color change to 3 or 4), when the amount of CD44 expressed in epithelial layers in leukoplakia decreased (**** p < 0.0001)." (PMID 34830890, 2021). "CD44 glycoprotein was detected also in the macrophages in lamina propria of oral leukoplakia." (PMID 34830890, 2021). "However, it should be noted that the comparison of paired associations between total protein, SolCD44, and mean number of CD44-positive expression in epithelial layers in leukoplakia tissue between the control group and patients with leukoplakia showed statistical significance (**** p < 0.0001)." (PMID 34830890, 2021). "In oral leukoplakia, the IHC reaction with anti-DEC1 showed a cellular distribution of 25–74% in most cells with weak to moderate intensity, while anti-CD44 demonstrated strong staining intensity within the same range of distribution." (PMID 40005368, 2025).
Oral leukoplakia (continued). "Three proteins—CD44, S100A7, and S100P—were significantly different in dysplastic leukoplakia compared to the normal cohort, with CD44 showing the highest sensitivity." (PMID 34830890, 2021). "In oral leukoplakias, CD9 expression was detected in the cell membrane at the same areas as CD44 and in an identical number of epithelial cell layers." (PMID 34830890, 2021). "In this retrospective study, the expression of TGF-B and CD44 were evaluated in 55 paraffin-embedded specimens (10normal mucosa, 15 non-dysplastic leukoplakia, 15 dysplastic leukoplakia, and 15 OSCC) by immunohistochemistry." (PMID 33681421, 2021). "Diagnostic accuracy of CD44 and TGF-B for differentiation of SCC and dysplastic leukoplakia from non-dysplastic leukoplakia and normalmucosa was assessed." (PMID 33681421, 2021). "Pairwise comparison of the groups for CD44 expression revealed significant differences in all cases except between patients with non-dysplastic leukoplakia and normal oral mucosa." (PMID 33681421, 2021). "A Significant increase in percentage of staining of CD44 non-dysplastic leukoplakia compared to dysplastic leukoplakia and OSCC indicated the connotation of these markers in the process of malignant transformation and detection of these lesions." (PMID 33681421, 2021). "The second purpose of the parallel examination of CD44 and CD9 proteins was to clarify whether CD9 participates in the transformation processes of oral leukoplakia into cancer." (PMID 34830890, 2021). "Therefore, it is of scientific and clinical interest that we found that both CD44 and CD9 antigens co-expressed in oral mucosa epithelial cell membranes in both healthy mucosa and oral leukoplakia." (PMID 34830890, 2021). "In non-homogenous oral leukoplakia, CD44 antigen was present not only in cytolemma of the epithelial cells of OL, but also in the cytoplasm of the affected epithelium." (PMID 34830890, 2021). "Thus, this study aimed to assess the expression of CD44 and TGF-B in OSCC and leukoplakia as a premalignant oral lesion." (PMID 33681421, 2021). "In cases of non-homogenous leukoplakia, CD44 expression was seen in, on average, 15 layers of the epithelium." (PMID 34830890, 2021). "Increased expression of CD44 as a cancer stem cell marker and TGF-B as an EMT marker from normal mucosa to non-dysplastic leukoplakia, dysplastic leukoplakia, and OSCC and also the significant correlation between these two markers indicated their role in carcinogenesis of oral mucosa." (PMID 33681421, 2021). "Therefore, the number of biopsies from non-homogeneous leukoplakias for the calculation of CD9- and CD44-positive epithelial layers must be increased in the future." (PMID 34830890, 2021). "Increased expression of CD44 as a CSC marker and TGF-B as a marker involved in EMT from normal mucosa to non-dysplastic leukoplakia, dysplastic leukoplakia and OSCC and the significant correlation between these two markers indicated their role in carcinogenesis of oral mucosa." (PMID 33681421, 2021). "It should be noted that according to the current results, CD44 had maximum sensitivity and specificity for differentiation of “SCC and dysplastic leukoplakia” from “non-dysplastic leukoplakia and normal mucosa” as well as differentiation of SCC from dysplastic leukoplakia." (PMID 33681421, 2021). "Evaluation of CD44 and TGF-B expression in the four studied groups showed statistical significant difference for each marker (p< 0.001).Pairwise comparison of CD44 and TGF-B expression in all groups except normal mucosa and non-dysplastic leukoplakia demonstrated statisticalsignificant difference." (PMID 33681421, 2021).
oral lichen planus (5 papers, 2020 to 2025). Oral lichen planus is a chronic inflammatory oral condition of unknown aetiology characterized by T-cell-mediated chronic immune response and abnormal epithelial keratinization cycle. "Inflammatory salivary marker levels (such as those of osteopontin and CD44) in patients with oral lichen planus were higher than those in healthy subjects." (PMID 34299815, 2021). "As has been observed, the expression of CD44 was significantly lower in OSCC in comparison with oral lichen planus which is a precancerous state of OSCC, indicating that CD44 might trigger the malignant conversion from precancerous state to cancer." (PMID 33303029, 2020).
pituitary adenoma (5 papers, 2015 to 2025). "CD44 has been identified as a molecular marker of invasive pituitary adenomas and is present in cancer stem‐like cells in endocrine tissues." (PMID 41017273, 2025). "As a result, we observed 84–98% of EpCAM-positive cells and 7–13% of CD44-positive cells, suggesting that most of the population belongs to the pituitary adenoma cells." (PMID 40002253, 2025). "Recent evidence indicates that CD44, CD34, PTTG, FGFR4, MMP9, E‐Cadherin, and N‐Cadherin serve as biomarkers of aggressive pituitary adenomas." (PMID 41017273, 2025).
prion disease (5 papers, 2019 to 2025). A transmissible disease that is caused by a protein that is able to induce abnormal folding of normal cellular proteins, leading to characteristic spongiform brain changes, which are associated with neuronal loss without an inflammatory response. "Early pathological changes during CNS prion disease also include reactive astrocyte activation with increased CD44 expression, microgliosis, as well as loss of dendritic spines and synapses." (PMID 38877012, 2024). "CD44 expression is linked to reactive astrocyte heterogeneity observed in the brain during prion disease in mice, and it was suggested as a biomarker to enhance the identification of distinct prion agent strains." (PMID 33375642, 2020). "Together, our data show that during CNS prion disease specific reactive astrocytes express high levels of CD44 and the splice variant form, CD44v6." (PMID 31551718, 2019). "In the current study, astrocyte responses to prion infection were characterized using anti-pan-CD44 and the splice variant specific anti-CD44v6 antibodies on a wide-range of mouse-adapted prion disease strains derived from sheep scrapie, BSE and CWD." (PMID 31551718, 2019). "Our observation that Icam1 expression is upregulated to a greater degree at 140 dpi in CD44−/− mice compared to WT mice during prion disease would support the hypothesis that deficiency in CD44 may be compensated for by Icam1 activity." (PMID 38877012, 2024). "Therefore, in the current study we used CD44-deficient mice to determine the role of CD44 in astrocyte and microglial responses and the development of the neuropathology during CNS prion disease." (PMID 38877012, 2024). "Here we used mice deficient in CD44 to determine the role of CD44 during prion disease." (PMID 38877012, 2024). "Whether the expression of other CD44 splice variants is similarly induced in astrocytes during prion disease remains to be determined." (PMID 31551718, 2019). "The accumulations of abnormally folded, prion disease-specific, relatively proteinase K (PK)-resistant PrP (termed PrPSc) were also similar in the brains of WT and CD44−/− mice following prion infection." (PMID 38877012, 2024). "In WT mice Icam1 accumulation was observed with a similar heterogenic and astrocytic pattern to CD44 in targeted brain areas such as the hippocampus at the terminal stage of prion disease." (PMID 38877012, 2024). "Despite this heterogeneity, this analysis also showed that Cd44 expression was significantly upregulated in most of the prion/host combinations studied from approximately 50% of the way through prion disease survival time." (PMID 38877012, 2024). "The development of CNS prion disease and, the magnitude of the PrPSc accumulation, prion induced vacuolation, microgliosis and reactive astrocytosis in the brains of prion-infected CD44−/− mice were similar to those observed in prion infected WT mice." (PMID 38877012, 2024). "Together, our data clearly show that CD44 expression in astrocytes during CNS prion disease is dispensable for the development of the reactive astrocytosis and neuropathology." (PMID 38877012, 2024). "Our data show that CD44 is dispensable for glial activation during prion disease or for prion neuropathogenesis." (PMID 38877012, 2024). "Together, our data show that although CD44 expression is upregulated in reactive astrocytes during CNS prion disease, it is dispensable for astrocyte and microglial activation and the development of prion neuropathogenesis." (PMID 38877012, 2024). "CNS prion disease is accompanied by extensive reactive astrocytosis characterized by high levels of expression of glial fibrillary acidic protein (GFAP), CD44 and the CD44v6 alternative splice variant." (PMID 35852018, 2022). "In the brains of mice with terminal ME7 prion disease CD44 immunostaining was observed in a wide range of areas and sub-regions." (PMID 31551718, 2019).